FSHR (follicle stimulating hormone receptor)
Diseases named in the same sentence as FSHR in open-access papers (continued):
Sharing a sentence is not in itself a finding about the gene and the disease.
Obesity (13 papers, 2014 to 2026). Accumulation of substantial excess body fat. "This study looks at how bariatric surgery affects endothelial nitric oxide synthase (eNOS) expression and reproductive hormone regulation across different follicle-stimulating hormone receptor (FSHR) polymorphism groups in women with extreme obesity." (PMID 39857651, 2024). "Understanding the interactions between obesity, biochemical pathways such as NO signaling, and genetic variants such as FSHR polymorphisms opens up new possibilities for improving reproductive health outcomes in affected individuals." (PMID 39857651, 2024). "Based on BMI and WHR, the criteria used for obesities, we investigated whether there was a correlation between obesity and the FSHR polymorphisms in PCOS patients." (PMID 24390680, 2014). "In conclusion, the molecular basis of obesity-related reproductive dysfunction emphasizes the importance of eNOS and FSHR." (PMID 39857651, 2024). "Nuclear genes, including calpain 10 (CAPN10), cytochrome family P450, insulin (INS) gene, androgen receptor (AR), fat mass obesity (FTO) gene, and follicle-stimulating hormone receptor (FSHR) gene, have been shown to be associated with PCOS." (PMID 37674615, 2023). "FTO (Fat mass and obesity associated gene; rs9939609), FSHB (Follicle stimulating hormone beta subunit; rs6169), FSHR (Follicle stimulating hormone receptor; rs6165/rs6166), and INSR (Insulin receptor; rs1799817) genes were genotyped using HRM assay." (PMID 30596735, 2018). "A preclinical study reported that female mice FSHR gene deficient (Fshr+/− mice) do not develop obesity as wild-type ovariectomized mice do." (PMID 32681384, 2020). "Analysis of the frequency of FSHR polymorphisms showed no statistical difference among the PCOS patients with different obesity standards." (PMID 24390680, 2014). "There were no statistical differences among the different obesity standards of the PCOS patients with different FSHR polymorphisms." (PMID 24390680, 2014). "Furthermore, the expression of LHR and FSHR in the ovaries was reduced, which further delayed the maturation of the ovaries and uterus, reversed the development of the gonadal axis and alleviated the symptoms of precocious puberty in obesity-induced precocious puberty rats." (PMID 36568086, 2022).
osteoporosis (11 papers, 2015 to 2025). A condition of reduced bone mass, with decreased cortical thickness and a decrease in the number and size of the trabeculae of cancellous bone (but normal chemical composition), resulting in increased fracture incidence. "In summary, targeting FSHR is a highly promising strategy for improving bone impairment associated with accelerated bone resorption in patients with osteoporosis or slowing disease progression in postmenopausal women and potentially other groups." (PMID 41393297, 2025). "FSHR have been implicated in bone metabolism, with specific mutations associated with osteoporosis and low BMD." (PMID 41393297, 2025). "In their work, Rendina and colleagues found that women carrying the FSHR rs6166 Asn/Asn variant had a higher postmenopausal osteoporosis risk than those with the Ser/Ser variant and that this SNP significantly influenced postmenopausal BMD." (PMID 41393297, 2025). "We have obtained three patient-specific cell lines from patient with osteoporosis, bearing this homozygous FSHR rs6166 Asn/Asn variant, and they all did show impaired osteoblasts maturation and mineralization capacity." (PMID 41393297, 2025). "In fact, the rs6166 FSHR genotype might help in stratifying the risk of developing osteoporosis and a monoclonal antibody against the FSHβ chain has shown promising results for the treatment of osteoporosis in the animal model." (PMID 31581477, 2019). "Thus, the FSHR rs6166 Asn/Asn variant may be considered as a diagnostic tool for stratifying the risk of osteoporosis." (PMID 41393297, 2025). "Recent extragonadal FSHR expression findings opened up novel possibilities for functional FSHR as a diagnostic, prognostic, and therapeutic tool for cancer therapy, potentially also for postmenopausal obesity bone mass/osteoporosis, angiogenesis or Alzheimer disease." (PMID 39633277, 2024). "In addition, the rs6166 FSHR genotype might be gathered as a diagnostic tool to stratify the risk of developing osteoporosis in the female sex." (PMID 31581477, 2019). "Direct role of FSHR in bone biology highlights its translational relevance, as a considerable importance of FSHR in pathogenesis of osteoporosis has been demonstrated, particularly in postmenopausal women." (PMID 41393297, 2025). "Specifically, we identified osteoporosis-associated SNPs in GPCR genes, which were linked to impaired osteogenic differentiation in vitro including ADRB2 as well as CNR2, MTNR1B, FSHR, TSHR, LGR4, CALCR and WLS." (PMID 41393297, 2025). "Recently, our study of postmenopausal women diagnosed with osteoporosis revealed a novel combination of three SNPs in GPCR genes — FSHR (rs6166), TSHR (rs1991517), and ADRB2 (rs1042713) — with a high frequency of approximately 20%." (PMID 41393297, 2025). "We found specific osteoporosis-linked SNPs in genes encoding key receptors involved in bone metabolism that are classified into rhodopsin (ADRB2, CNR2, MTNR1B, FSHR, TSHR, LGR4), secretin (CALCR, GIPR), and other T7M (WLS) receptor families." (PMID 39769358, 2024). "Missense mutations in ADRB2, CNR2, FSHR, TSHR, CALCR, and GIPR genes were earlier associated with decreased BMD and osteoporosis in postmenopausal women as leading to amino acid substitutions and the possible receptor structure and/or function change." (PMID 39769358, 2024). "However, the research promoted after the identification of FSH effects on bone tissue has led to studies aimed at exploring its protective role against the development of osteoporosis in women with the FSHR rs6166 GG genotype; thus supporting extra-gonadal effects that FSH may likely have." (PMID 32681384, 2020). "Although missense mutations in FSHR, TSHR, and ADRB2 have previously been associated with reduced BMD and osteoporosis, the combined effect of these specific SNPs has not yet been considered as a potential prognostic marker." (PMID 41393297, 2025).
osteoporosis (continued). "FSH receptor (FSHR) and FSHβ knockout ovariectomized mice do not develop bone loss, suggesting that the FSH/FSHR pathway is involved in the pathogenesis of osteoporosis." (PMID 31581477, 2019).
hypogonadism (10 papers, 2011 to 2025). A disorder characterized by decreased function of the gonads. "Genetic deletion of the FSHβ subunit (FSHβ-/- mice) or FSH receptor (FSHR-/- mice) protects against bone loss despite severe hypogonadism, demonstrating a contribution of FSH in hypogonadal bone loss." (PMID 33767633, 2021). "As shown in the previous study, the FSHR knock-out mice exhibit severe hypogonadism, characterized by irregular estrous cycles, ovulatory abnormalities, atrophic ovaries, and a thread-like uterus suggestive of pronounced estrogen deficiency." (PMID 39498265, 2024). "FSHR knockout mice exhibited severe hypogonadism, and FSH levels increased sharply in parallel; however, their bone mass was normal." (PMID 26241313, 2015).
colon carcinoma (8 papers, 2013 to 2023). "A recent study confirmed our hypothesis that interruption of the endothelial FSH/FSHR signaling on colon tumor-associated blood vessels induces reduction of tumor vasculature, radiological stabilization and carcinoembryonic antigen stabilization during 1 year." (PMID 25652007, 2015). "Mutations in genes encoding GPCRs are observed in approximately 20% of cancers, including mutations in TSHR in thyroid cancer, luteinizing hormone receptor (LHCGR), and follicle stimulating hormone receptor (FSHR) in breast, lung, and colon cancers." (PMID 31072060, 2019). "Among brain metastases, the density of FSHR-positive vessels was highest in lung and kidney cancer, and lowest in prostate and colon cancer." (PMID 23688201, 2013). "Recent cancer genome mutation analyses have revealed that GPCRs are mutated in roughly 20% of all malignancies, including mutations in the thyroid hormone receptor (TSHR), the luteinizing hormone receptor (LHCGR), and follicle-stimulating hormone receptor (FSHR) in breast, lung, and colon cancers." (PMID 34943797, 2021).
hypothyroidism (8 papers, 2011 to 2025). Abnormally low levels of thyroid hormone. "Extremely high concentrations of TSH in hypothyroidism may be sufficient to cause the activation of FSHR." (PMID 21861901, 2011). "However, spontaneous OHSS, occurring without such intervention, is rarely reported and often linked to elevated endogenous human chorionic gonadotropin (hCG) levels, as seen in molar pregnancies or multifetal gestations, hypothyroidism, or mutations in the FSH receptor (FSHR) gene." (PMID 41356863, 2025). "However, Follicular Stimulating Hormone (FSH)-producing pituitary adenomas (FSHoma) or neuroendocrine tumors, activating mutations of the FSH receptor (FSHR), and hypothyroidism may also constitute risky situations." (PMID 28446136, 2017).
hyperandrogenism (7 papers, 2015 to 2024). Excessive secretion of androgens from the adrenal glands or gonads. "Pathophysiological functions of genes are primarily responsible for the synthesis of proteins that have role in PCOS before hyperandrogenism including GnRHR, FSHβ, FSHR, LHCGR, CYP19A1, HSD17B, AR and SHBG, and their effects in PCOS of human have been confirmed." (PMID 30944702, 2019). "Genetic polymorphisms in GnRH and gonadotrophic hormone receptors affect the phenotype of PCOS; FSHR Ser was related to higher levels of FSH and a higher frequency of hyperandrogenism." (PMID 37629254, 2023).
pituitary adenomas (7 papers, 2013 to 2025). "The results of these tests argued against the secretory activity of the pituitary adenoma in terms of gonadotropin secretion and for an abnormality in the action of endogenous gonadotropins, which was later confirmed by the genetic test result revealing the mutation in the FSHR gene." (PMID 40917349, 2025). "In pituitary adenomas, the expression of FSHR in tumoral cells is prevalent in invasive and proliferating, it means more aggressive tumours." (PMID 25685198, 2015).
amenorrhea (6 papers, 2012 to 2024). The absence of menses in a woman who has achieved reproductive age. "The rs6165 and rs6166 gene polymorphism of FSHR are associated with female menstruation and can be used as a relevant molecular biomarker to identify the risk of amenorrhea in our population." (PMID 37255590, 2023). "The single nucleotide polymorphism of the FSHR gene to amino acid positions 307 (rs6165) might consider as one of the susceptible factors that result in amenorrhea (Nijeeb, Alkazaz & Yaseen, 2020)." (PMID 37255590, 2023). "However, there is little knowledge about this in Iraq, so this study could help to seek the main genetic cause of amenorrhea and investigated the effect of FSHR gene polymorphism (Ala307Thr and Ser680Asn) with altered ovarian response in amenorrhoeic women." (PMID 37255590, 2023). "Additionally, a recent case report suggested that vismodegib might induce amenorrhea by blockading follicle-stimulating hormone receptor-dependent signal transduction." (PMID 27581207, 2016).
Hypergonadotropic hypogonadism (6 papers, 2015 to 2025). Reduced function of the gonads (testes in males or ovaries in females) associated with excess pituitary gonadotropin secretion and resulting in delayed sexual development and growth delay. "FSH and FSHR mutations or FSHR SNPs should always be suspected in the case of the coexistence of hypergonadotropic hypogonadism, low testicular volume, and reduced seminogram parameters after excluding Klinefelter syndrome and secondary testicular damage." (PMID 40917349, 2025). "We present here the case of an elite athlete with hypergonadotropic hypogonadism caused by an FSHR causing-disease variant." (PMID 40917349, 2025). "In hypergonadotropic hypogonadism, both human and animal data suggest a pathological desensitization of the FSH receptor (FSHR) caused by high circulating levels of gonadotrophins." (PMID 35526153, 2022). "A pathogenic homozygous missense variant in FSHR was identified in two siblings presenting with hypergonadotropic hypogonadism using whole-exome sequencing and references therein." (PMID 33095795, 2020). "Numerous inactivating FSHR mutations have been described such as Ala189Val in the FSHR ECD leading to hypergonadotropic hypogonadism with no or weak response to FSH." (PMID 25767463, 2015). "FSHR encode follicle-stimulating hormone (FSH), and anydysfunctions in this receptor may disturb the function of follicles and ovaries.Mutations which inactivate FSHR will lead to hypergonadotropic hypogonadism, whichcan cause the follicles to stagnate in the preantral state." (PMID 36350975, 2023).
Alzheimer disease (5 papers, 2019 to 2025). A progressive, neurodegenerative disease characterized by loss of function and death of nerve cells in several areas of the brain leading to loss of cognitive function such as memory and language. "FSH receptor (FSHr) is expressed in the cerebral cortex and hippocampus, and its blockade has been shown to slow the progression of Alzheimer’s disease in women." (PMID 40722636, 2025).
granulosa cell tumor (5 papers, 2016 to 2024). A slow-growing, malignant tumor, characterize by the presence of granulosa-like cells and Call-Exner bodies, that is almost always found in the ovary. "Prior studies have implicated β-arrestins in inhibiting GPCR-mediated apoptosis, including FSH/FSHR mediated apoptosis in granulosa cell tumor lines and in cancer invasion and metastasis." (PMID 35185785, 2021). "The human granulosa cell tumor sections used as positive control showed FSHR transcript localization in carcinoma cells (higher magnification inserts)." (PMID 27848975, 2016). "FSHR mRNA was localized in granulosa cell tumor controls, but not in umbilical cord vein." (PMID 27848975, 2016).
metastatic tumors (5 papers, 2013 to 2024). "FSHR is expressed in 11 human solid tumor types, 11 types of soft-tissue sarcomas, and in the majority of metastatic tumors." (PMID 33920299, 2021). "This last observation suggests a link between FSHR expression and angiogenesis in metastatic tumors." (PMID 23688201, 2013). "Continued investigation into FSHR expression in various tumor types, such as low-grade T1 and metastatic tumors, may facilitate the development of tumor-specific fluorescent agents to assess surgical margins." (PMID 37568488, 2023). "FSHR is expressed by the endothelium of blood vessels in the majority of metastatic tumors." (PMID 23688201, 2013). "Our data show that FSHR is expressed by the microvasculature of metastatic tumors." (PMID 23688201, 2013). "In the particular case of FSHR expression, a legitimate question is whether it is generally expressed by the endothelium of metastatic tumors, as it is in the primary tumors." (PMID 23688201, 2013).
serous ovarian cancer (5 papers, 2018 to 2024). "OVCAR4, a high-grade serous ovarian adenocarcinoma cell line, is reported to have distinct positive expression of the surface receptor; FSHR and D2AP11-TCE induced potent killing in this cell line in the presence of human PBMCs as well as human T cells." (PMID 36509287, 2022). "Knockdown of FSHR significantly increased the invasion of serous ovarian cancer cells (OVCAR3 and COV362) in vitro." (PMID 33374698, 2020). "The increased invasion following FSHR knockdown observed in serous ovarian cancer cells supports the findings observed in the FORKO mouse model which lacks FSHR." (PMID 33374698, 2020). "An FSHR antibody (H-190, Santa Cruz Biotechnology) detected protein bands at ∼48 kDa, ∼55 kDa and ∼65 kDa in the serous ovarian cancer tissue extracts shown to express FSHR in immunohistochemistry." (PMID 33374698, 2020). "Whilst FSHR mRNA was only detected in the positive control KGN cells and normal human ovary, FSHR protein expression was observed in KGN cells as well as in serous ovarian cancer cell lines." (PMID 33374698, 2020). "Knockdown of FSHR or LHCGR expression increased invasion of serous ovarian cancer cells." (PMID 33374698, 2020). "FSHR mRNA expression was found in KGN granulosa tumor cell line and positive control human ovary tissue but was undetectable in the serous ovarian cancer cell lines." (PMID 33374698, 2020). "Two serous ovarian cancer cell lines, OVCAR3 and COV362, which expressed both FSHR and LHCGR, were selected for the gonadotropin receptor knockdown and invasion studies below." (PMID 33374698, 2020). "The follicle stimulating hormone receptor (FSHR) is selectively expressed in ovarian granulosa cells and different histological types of OC, including 50-70% of serous ovarian carcinomas, but not in other healthy tissues apart from ovaries." (PMID 37274261, 2023). "A follow-up study by the same group investigating hormone receptor expression in a small cohort of low grade serous ovarian cancer (n = 26) did not observe a relationship with FSHR expression and patient survival." (PMID 33374698, 2020). "In addition, we investigated the effect of FSHR and LHCGR siRNA knockdown on the pro-metastatic behavior of serous ovarian cancer cells in vitro." (PMID 33374698, 2020). "Moreover, FSHR expression is detected in 54.5% of 875 high-grade serous ovarian cancer tissues and is not related to progression-free survival or overall survival." (PMID 29461120, 2018).
testicular cancer (5 papers, 2019 to 2024). A primary or metastatic malignant neoplasm that affects the testis. "FSHR has been reported in several types of cancers including testicular cancer." (PMID 35676718, 2022). "In addition, the abundance of FSHR in patients with primary renal carcinoma was nearly comparable to that in testicular cancer, in which the surge was different from the physiologically low FSHR expression in the kidneys." (PMID 31243899, 2019). "Regarding testicular cancer, overexpression of FSHR has been observed in embryonal carcinomas in comparison to seminomas, the latter showing absent FSHR expression." (PMID 37375761, 2023).
Autoimmunity (4 papers, 2012 to 2022). The occurrence of an immune reaction against the organism's own cells or tissues. "Although there is evidence that ROS is linked to autoimmune disorders, few cases have been reported in which Ig-FSHR antibodies were detected or corresponding immunotherapy was administered to patients with ROS." (PMID 35392972, 2022). "It is therefore unlikely that autoimmunity to the LHR or FSHR constitutes a frequent cause of hyperandrogenemia or ovulatory dysfunction in PCOS." (PMID 34948471, 2021). "The prevalence of positive samples was similar in both cohorts, i.e., there was no obvious quantitative difference in autoimmunity against the FSHR and LHR in controls and PCOS patients." (PMID 34948471, 2021). "However, our results do not support the hypothesis of a relevant role of FSHR-aAb or LHR-aAb as a frequent cause of PCOS, indicating that other autoantigens may be targets of relevant autoimmunity in PCOS." (PMID 34948471, 2021).
diabetes (4 papers, 2018 to 2025). "Relatedly, one study revealed that ovaries from mice with STZ-induced diabetes were significantly smaller compared to those of control mice, accompanied by decreased expression of follicle-stimulating hormone receptor and luteinizing hormone/choriogonadotropin receptor." (PMID 40110863, 2025). "Since FSH primarily exerts its biological function through binding to the FSH receptor (FSHR), it suggests FSHR may be a potential therapeutic target for diabetes control in overweight or obese postmenopausal women." (PMID 36767197, 2023).